CYP26B1 (cytochrome P450 family 26 subfamily B member 1)
Description:
A cytochrome P450 monooxygenase involved in the metabolism of retinoates (RAs), the active metabolites of vitamin A, and critical signaling molecules in animals. RAs exist as at least four different isomers: all-trans-RA (atRA), 9-cis-RA, 13-cis-RA, and 9,13-dicis-RA, where atRA is considered to be the biologically active isomer, although 9-cis-RA and 13-cis-RA also have activity (Probable). Catalyzes the hydroxylation of atRA primarily at C-4 and C-18, thereby contributing to the regulation of atRA homeostasis and signaling. Hydroxylation of atRA limits its biological activity and initiates a degradative process leading to its eventual elimination. Involved in the convertion of atRA to all-trans-4-oxo-RA. Can oxidize all-trans-13,14-dihydroretinoate (DRA) to metabolites which could include all-trans-4-oxo-DRA, all-trans-4-hydroxy-DRA, all-trans-5,8-epoxy-DRA, and all-trans-18-hydroxy-DRA (By similarity). Shows preference for the following substrates: atRA > 9-cis-RA > 13-cis-RA. Plays a central role in germ cell development: acts by degrading RAs in the developing testis, preventing STRA8 expression, thereby leading to delay of meiosis. Required for the maintenance of the undifferentiated state of male germ cells during embryonic development in Sertoli cells, inducing arrest in G0 phase of the cell cycle and preventing meiotic entry. Plays a role in skeletal development, both at the level of patterning and in the ossification of bone and the establishment of some synovial joints. Essential for postnatal survival (By similarity). Also has a significant activity in oxidation of tazarotenic acid and may therefore metabolize that xenobiotic in vivo.
Synonyms: CYP26A2; P450RAI2; P450RAI-2; RHFCA
Tractability: Small molecule: a high-quality ligand is known; it belongs to a druggable protein family. Antibody: UniProt places it where antibodies can reach, with medium confidence. PROTAC: ubiquitination databases record sites on it; a small molecule that binds it is known.
Target class: Cytochrome P450; Cytochrome P450 family 26; Enzyme
Gene: Protein-coding gene on chromosome 2 (72,129,238 to 72,147,862, reverse strand). Ensembl gene ENSG00000003137.
Subcellular location: Endoplasmic reticulum membrane; Microsome membrane
Subcellular location (Human Protein Atlas): Cytosol
Pathways (Reactome):
Disease: Defective CYP26B1 causes RHFCA
Metabolism: Vitamins
Signal Transduction: RA biosynthesis pathway
Gene Ontology:
Molecular function: oxidoreductase activity, acting on paired donors, with incorporation or reduction of molecular oxygen, NAD(P)H as one donor, and incorporation of one atom of oxygen; protein binding; retinoic acid 4-hydroxylase activity; retinoic acid binding; heme binding; all-trans retinoic acid 18-hydroxylase activity; iron ion binding; monooxygenase activity; oxidoreductase activity, acting on paired donors, with incorporation or reduction of molecular oxygen; oxidoreductase activity, acting on paired donors, with incorporation or reduction of molecular oxygen, reduced flavin or flavoprotein as one donor, and incorporation of one atom of oxygen
Biological process: bone morphogenesis; retinoic acid catabolic process; retinoic acid metabolic process; xenobiotic metabolic process; cell fate determination; central nervous system development; embryonic limb morphogenesis; male meiotic nuclear division; negative regulation of retinoic acid receptor signaling pathway; proximal/distal pattern formation; spermatogenesis; vitamin metabolic process; cellular response to retinoic acid; kidney development; positive regulation of gene expression; positive regulation of tongue muscle cell differentiation; response to retinoic acid; response to vitamin A; tongue morphogenesis
Cellular component: cytoplasm; endoplasmic reticulum membrane
Genetic constraint (gnomAD): Loss-of-function variants: 8 observed, 38.95 expected, observed/expected ratio (o/e) 0.21, 90% interval 0.12 to 0.37. The upper end of that interval is the gene's LOEUF score, 0.37, which puts it in group 1 of 6, group 1 being the genes least tolerant of losing a copy. Missense variants: 615 observed, 708.51 expected, observed/expected ratio (o/e) 0.87, 90% interval 0.81 to 0.93. Synonymous variants: 321 observed, 313.23 expected, observed/expected ratio (o/e) 1.02, 90% interval 0.94 to 1.12.
Gene-disease validity (ClinGen):
ClinGen rates the evidence that CYP26B1 causes each of these diseases.
lethal occipital encephalocele-skeletal dysplasia syndrome (autosomal recessive): Moderate.
Homologues: Orthologues: chimpanzee CYP26B1 (99% identical), macaque CYP26B1 (99% identical), guinea pig CYP26B1 (98% identical), pig CYP26B1 (97% identical), dog CYP26B1 (97% identical), mouse Cyp26b1 (96% identical), rat Cyp26b1 (96% identical), tropical clawed frog cyp26b1 (85% identical), rabbit CYP26B1 (78% identical), zebrafish cyp26b1 (75% identical). Paralogues in human: CYP26C1 (53% identical), CYP26A1 (42% identical).
Diseases named in the same sentence as CYP26B1 in open-access papers:
CYP26B1 is named in the same sentence as 85 diseases in open-access papers, as found by Europe PMC text mining. Sharing a sentence is not in itself a finding about the gene and the disease. The quoted sentences say what the papers report.
craniosynostosis (8 papers, 2013 to 2025). Craniosynostosis is defined as the premature fusion of one or more cranial sutures leading to secondary distortion of skull shape resulting in skull deformities with a variable presentation. "Absent or short first digit and mesoaxial/all‐fingers syndactyly, associated with craniosynostosis, suggests CYP26B1‐related disease and Apert syndrome, respectively." (PMID 40673520, 2025). "Craniosynostosis was first modeled in zebrafish through loss-of-function mutations in cyp26b1, reproducing coronal craniosynostosis observed in human patients." (PMID 36225206, 2022). "Accordingly, partial loss of cyp26b1 activity causes coronal craniosynostosis through accelerated osteoblast to (pre) osteocyte transition." (PMID 31835881, 2019). "Previously, in two other families, two different homozygous mutations of CYP26B1 have been reported, resulting in lethality, skeletal and craniofacial abnormalities, including fusion of long bones, calvarial bone hypopasia and craniosynostosis." (PMID 23837398, 2013). "Cytochrome P450 Subfamily 26B polypeptide 1 (CYP26B1, MIM *605207) biallelic variants have been associated with a condition termed ‘Craniosynostosis with radiohumeral fusions and other skeletal and craniofacial anomalies’ (MIM #614416)." (PMID 40673520, 2025). "Along these lines, and specifically regarding the observed craniosynostosis in Cyp26b1 mutants, it has been shown that cranial suture-derived mesenchymal cells enhance osteogenesis upon RA treatment." (PMID 24340023, 2013). "This might explain why cyp26b1 amorphs do not display craniosynostosis, as the frontal and parietal calvarial plates are reduced in size and, therefore, not able to form a proper suture." (PMID 31835881, 2019).
pharyngeal cancer (7 papers, 2013 to 2023). "In conclusion, this study suggested that BQ chewers with ROS related to CYP26A1 and CYP26B1 polymorphisms are associated with an increased risk of oral and pharyngeal cancer and OPMDs." (PMID 25839051, 2015). "Our previous studies indicating that arecoline induces both in vivo and in vitro suggest that the CYP26B1 variants play a vital role in BQ-related oral and pharyngeal cancers." (PMID 25114974, 2014). "Our previous studies reported that CYP26B1 variants are associated with oral and pharynx cancers and that the expression of the CYP26B1 spliced variant may be related to oral and pharynx cancers." (PMID 33233443, 2020). "The CYP26B1 rs3768647 G allele may be associated with oral and pharyngeal cancer (aOR = 3.12) and OPMDs (aOR = 2.23)." (PMID 25839051, 2015). "BQ chewers with the CYP26A1 rs4411227 C allele and CYP26B1 rs3768647 G allele had the highest risk of oral and pharyngeal cancer compared with the subjects carrying the CYP26A1 rs4411227 G allele and CYP26B1 rs3768647 C allele (aOR = 29.91; 95% CI = 10.75–83.23)." (PMID 25839051, 2015). "Thus, the specific aim of this association study was to investigate the role of CYP26 family (CYP26A1 and CYP26B1) single nucleotide polymorphisms (SNPs) in the risk of OPMDs and oral and pharyngeal cancers." (PMID 25839051, 2015). "We investigated whether susceptible CYP26B1 genes and, particularly, their splicing variants are associated with oral and pharyngeal cancer." (PMID 25114974, 2014). "We investigated whether a splice variant of CYP26B1 is associated with the occurrence of ROS related oral and pharyngeal cancer." (PMID 25114974, 2014). "Recently, studies have suggested that SNPs of CYP26 family genes, such as CYP26A1, CYP26B1, and CYP26C1, were associated with susceptibility to oral and pharyngeal cancers." (PMID 31465460, 2019). "We hypothesized that two important SNPs (CYP26B1 rs887844 and CYP26C1 rs12256889) within CYP26 may significantly elevate genetic susceptibility to oral and pharyngeal cancers and OPMD." (PMID 31465460, 2019). "BQ chewers with the CYP26A1 rs4411227 C allele and CYP26B1 rs9309462 C allele had the highest risk of oral and pharyngeal cancer compared with the subjects carrying the CYP26A1 rs4411227 G allele and CYP26B1 rs9309462 T allele (aOR = 10.03; 95% CI = 1.05–95.60)." (PMID 25839051, 2015). "Increased expression of CYP26B1 was identified in betel quid (BQ)-related OSCC tumor tissues, and could be a novel biomarker for BQ-related oral and pharyngeal cancers." (PMID 36966276, 2023).
schizophrenia (6 papers, 2013 to 2024). A major psychotic disorder characterized by abnormalities in the perception or expression of reality. "Cyp26b1 has been associated with Schizophrenia in several human GWAS." (PMID 35237186, 2022). "Seven genes were investigated and involved in the synthesis, degradation and transportation of RA, ALDH1A1, ALDH1A2, ALDH1A3, CYP26A1, CYP26B1, CYP26C1 and Transthyretin (TTR), for their roles in the development of schizophrenia." (PMID 24564241, 2013).
colorectal cancer (5 papers, 2014 to 2025). A primary or metastatic malignant neoplasm that affects the colon or rectum. "Previous studies have shown that high expression levels of CYP26B1 enhance the cell survival properties of breast carcinoma cells and are significantly associated with poor prognosis in colorectal cancer." (PMID 36360213, 2022). "Additionally, CYP1A1, a key Phase I DME, has previously been linked to increased breast cancer risk, while high CYP26B1 has been associated with poor prognosis in colorectal cancer." (PMID 39997761, 2025). "This study has shown that the retinoic acid metabolising enzymes CYP26A1, CYP26B1 and LRAT are significantly overexpressed in colorectal cancer and that CYP26B1 and LRAT are significantly associated with prognosis both in the total cohort and in those tumours which are mismatch repair proficient." (PMID 24608339, 2014). "In addition, a previous study indicated that RA metabolizing enzymes CYP26B1 are overexpressed significantly in colorectal cancer and that CYP26B1 is significantly associated with the prognosis of colorectal cancer patients." (PMID 25114974, 2014). "A recent study demonstrated that the retinoic acid-metabolizing enzymes CYP26A1 and CYP26B1 are significantly overexpressed in colorectal cancer tissue." (PMID 25839051, 2015). "The CYP26 enzymes have been proposed as anti-cancer drug targets and the increased expression of CYP26A1 and CYP26B1 in colorectal cancer would suggest that these enzymes may be relevant therapeutic targets in this type of tumours." (PMID 24608339, 2014). "The relationship of the expression of CYP26A1, CYP26B1 or LRAT and survival in MMR proficient and defective colorectal cancers." (PMID 24608339, 2014). "Comparison of CYP26A1, CYP26B1 and LRAT expression in normal colonic mucosa, primary colorectal cancer and lymph node metastasis." (PMID 24608339, 2014). "The intensity of immunostaining was significantly higher in primary colorectal cancer compared with normal colonic mucosa for CYP26A1 (p = 0.002), CYP26B1 (p<0.001) and LRAT (p<0.001)." (PMID 24608339, 2014). "This study has defined the expression profile of the retinoic acid metabolising enzymes CYP26A1, CYP26B1 and CYP26C1 which are members of the P450 family of enzymes and LRAT in a large cohort of well characterised colorectal cancers." (PMID 24608339, 2014). "Epidemiological evidence has also proposed targeting of retinoids and the retinoic acid pathways for chemoprevention of colorectal cancer and the increased expression of CYP26A1 and CYP26B1 in colorectal cancer would indicate that targeting these enzymes may be a useful approach." (PMID 24608339, 2014). "CYP26B1 which was independently prognostic in a multivariate model both in the whole patient cohort and in MMR proficient tumours represents a new biomarker of colorectal cancer and CYP26B1 may represent a novel drug target for this type of tumour." (PMID 24608339, 2014).
neuroblastoma (4 papers, 2007 to 2025). Neuroblastoma (NB) is the most common solid, extracranial childhood tumor. "Studies have shown that CDK5R2 CYP26B1, DCAF8L1, PAGE1, and TRIM36 can be used to construct prognostic models or prognostic biomarker for HCC, rectal cancer, neuroblastoma, etc." (PMID 38649860, 2024). "With the exception of CYP26B1, we did not detect increased expression of analyzed RA target genes that we had identified in the neuroblastoma model in HL cells, indicating cell type specificity of these targets." (PMID 23409080, 2013).
atherosclerosis (3 papers, 2015 to 2024). A disease characterized by the build-up of fatty material and calcium deposition in the arterial wall resulting in partial or complete occlusion of the arterial lumen. "This study also reported an association between aggravated atherosclerosis with an SNP in the CYP26B1 gene with a greater retinoic acid catabolic activity." (PMID 38319073, 2024). "Moreover, a hyperactive CYP26B1 polymorphism (rs2241057, Leu264Ser) may aggravate atherosclerosis." (PMID 33724958, 2021). "Increased expression of CYP26B1 may aggravate atherosclerosis." (PMID 25958224, 2015).
colitis (3 papers, 2013 to 2022). Inflammation of the colon. "The passive transfer of naïve cytochrome p450 family 26 subfamily b1-deficient (Cyp26b1−/−) mice CD4 T cells into recombination-activating gene 1-deficient (Rag1−/−) mice resulted in a significantly reduced disease state in a model of T cell-dependent colitis." (PMID 30158832, 2018). "In the liver, colitis reduced the mRNA levels of Aldh1a1, Cyp26a1, and Cyp26b1, suggesting reduced production as well as oxidation." (PMID 35889745, 2022). "Thus, together with our observed comparable suppressive function between Cyp26b1fl/fl and Cyp26b1−/− Treg cells in vitro, the role of Cyp26b1 in Treg cell function in our T cell transfer colitis model is likely negligible." (PMID 23991089, 2013). "Our results show that T cell-specific expression of Cyp26b1 is required for the development of T cell-mediated colitis and may be applicable to the development of therapeutics that target Cyp26b1 for the treatment of inflammatory bowel disease." (PMID 23991089, 2013). "We next assessed whether Cyp26b1−/− T cells have an impaired ability to express intestinal homing molecules as a possible reason for why these T cells failed to cause disease in our colitis transfer model." (PMID 23991089, 2013). "In this context, CYP26B1, which is responsible for the catabolism of RA, has been shown to regulate the differentiation and function of CD4 T cells during experimental colitis, driving the cells towards an inflammatory profile." (PMID 30158832, 2018). "In adipose tissue, colitis mice had increased Cyp26b1 mRNA levels without increasing the expression of Aldh1a1, suggesting reduced RA concentration." (PMID 35889745, 2022).
hypervitaminosis A (3 papers, 2017 to 2023). A symptom complex resulting from ingesting excessive amounts of vitamin A. "We hypothesize here that excess vitamin A induces Vegfa expression and contributes to the bone phenotypes seen in human CYP26B1 deficiency and rat hypervitaminosis A." (PMID 30003121, 2018). "We show that bone from a human with CYP26B1 mutations displayed periosteal osteoclasts in piles within deep resorption pits, a pathognomonic sign of hypervitaminosis A. Analysis of the human angulated fetal femur revealed excessive bone formation in the marrow cavity and abundant blood vessels." (PMID 30003121, 2018). "These histological findings are comparable with data from hypervitaminosis A in rats, Cyp26b1 knockout mice, and zebrafish." (PMID 37755482, 2023). "In fact, we previously identified elevated Vegfa (and Cyp26b1) levels in bone tissue of rats with hypervitaminosis A, using microarray analysis and earlier studies show increased production/release of Vegfa from mouse osteoblasts and other cell types/tissues upon RA treatment." (PMID 30003121, 2018).
oral cancer (3 papers, 2013 to 2021). "According to our thorough review of relevant research, no previous study has explored the relationship between the expression activity of the CYP26B1 splice variant and oral cancer." (PMID 25114974, 2014). "Our results suggested that the CYP26B1 splice variant is associated with the occurrence of BQ-related oral cancer." (PMID 25114974, 2014). "Increased expression of the CYP26B1 splice variant was observed in human oral cancer tissue compared with adjacent normal tissue, and increased expression was observed in patients at a late tumor stage." (PMID 25114974, 2014). "Using paired human oral cancer tissues with long-term chewing habits, we confirmed that the expression of the CYP26B1 splice variant was consistently higher in oral cancerous tissues than in adjacent noncancerous tissues." (PMID 25114974, 2014). "The oral cancer tissue exhibited consistent upregulation in the protein levels of the CYP26B1 splice variant." (PMID 25114974, 2014). "Because this research was more difficult to get paired tissue specimen, we suggested that the future research needs a larger number of samples to confirm expression of a splice variant of CYP26B1 in betel quid-related oral cancer." (PMID 25114974, 2014). "We found that the CYP26B1 polymorphism AA significantly correlated with the risk of oral cancer (OR = 2.26; 95% CI, 1.35–3.80), and BQ chewers with the AA genotype had a significantly increased risk of oral cancer (OR = 70.04; 95% CI, 13.62–360.11)." (PMID 23983642, 2013). "We observed an association between a splice variant of CYP26B1 and BQ-related oral cancer, thus providing insight into the molecular mechanism of full-length CYP26B1 and a splice variant of CYP26B1 as well as their joint effects in the development of BQ-related oral cancer." (PMID 25114974, 2014). "In addition, the findings of our previous study suggest that the combination of higher CYP26B1 expression and polymorphism is associated with an increased risk of oral cancer." (PMID 23983642, 2013). "However, the physiologic importance of the increased induction rate and quantity of CYP26B1 by arecoline, accompanied by ROS generation in oral cancer cells, requires further investigation." (PMID 25114974, 2014). "We concluded that CYP26B1 is a novel candidate gene in the development of BQ-related oral cancer and speculated that CYP26B1 may be involved in the metabolism of arecoline-related compounds." (PMID 23983642, 2013). "In terms of the cytochrome p450 (CYP) metabolism pathway, the polymorphisms of CYP-involved genes (e.g., CYP26B1, CYP1A1, CYP2A6, and CYP2E1) have been found to activate areca nut (AN)-derived nitrosamines, thereby significantly increasing the susceptibility to tobacco-induced oral cancer." (PMID 34422810, 2021). "We detected higher levels of CYP26B1 mRNA and protein expression in human oral cancer cells compared with adjacent noncancerous tissues." (PMID 23983642, 2013).